IL2 (interleukin 2)
Diseases named in the same sentence as IL2 in open-access papers (continued):
Sharing a sentence is not in itself a finding about the gene and the disease.
chronic graft versus host disease (46 papers, 2010 to 2026). Chronic graft versus host disease (GVHD) is a complication that can occur after a stem cell or bone marrow transplant in which the newly transplanted donor cells attack the transplant recipient's body. "A recent study using samples from patients who received low-dose IL-2 demonstrated that the increased Treg diversity after IL-2 treatment was associated with the improvement of clinical symptoms of chronic GVHD." (PMID 34526990, 2021). "We first demonstrated that chronic GVHD is characterized by constitutive phosphorylation of Stat5 in Tcon, associated with elevated levels of IL-7 and IL-15 and relative functional deficiency of IL-2." (PMID 34526990, 2021). "Our previous controlled, open‐label randomized trial has indicated that a low dose of IL‐2 administration at Day 60 reduced the incidence of chronic GVHD (cGVHD) and translated into improved GVHD progression‐free survival (GPFS) post allo‐HSCT." (PMID 41550465, 2026). "Pharmacologically, Treg expansion can be promoted by subcutaneous injection of Interleukin-2 (IL-2), as demonstrated in chronic GvHD." (PMID 40387984, 2025). "IL-2 is critical for Treg homeostasis, and administration of a low dose of IL-2 to patients with active chronic GVHD restores Treg homeostasis and ameliorates clinical symptoms." (PMID 37092551, 2023). "It has been reported that low-dose IL-2 therapy increased circulating Tregs and improved clinical symptoms of chronic GVHD." (PMID 35983059, 2022). "Based on these findings, a phase 1 trial of administering low-dose IL-2 daily in patients with steroid-refractory chronic GVHD was conducted." (PMID 35983059, 2022). "The results led to the subsequent project of low-dose IL-2 therapy which aimed to reconstruct immune tolerance by increasing Tregs in patients with chronic GVHD." (PMID 34526990, 2021). "In the context of HSCT, preclinical data has shown that IL-2/anti-IL-2 antibody complexes have the capacity to expand Tregs and ameliorate chronic GVHD, a low inflammatory disease, while aggravating acute GVHD, a high inflammatory disease." (PMID 34575843, 2021). "Taken together, low-dose IL-2 therapy restores Treg homeostasis and promotes the reestablishment of immune tolerance in patients with chronic GVHD." (PMID 34526990, 2021). "Ongoing phase I/II clinical trials are currently testing molecularly engineered IL-2 with an increased half-life in patients with steroid-refractory chronic GVHD (NCT03422627) or systemic lupus erythematosus (NCT04680637 and NCT04433585)." (PMID 34575843, 2021). "Based on the theory that Tregs preferentially respond to low-dose IL-2, we conducted a phase 1 trial of administering low-dose IL-2 therapy daily in patients with steroid-refractory chronic GVHD (SR-cGVHD)." (PMID 34526990, 2021). "We also examined circulating Tregs from patients with chronic GVHD who were receiving low-dose IL-2 and found that IL-2-induced Treg proliferation was promptly followed by increased PD-1 expression on central-memory Tregs." (PMID 34526990, 2021). "Recent clinical data has demonstrated that low dose IL-2 infusions can substantially augment pTreg frequency and reduce disease severity in in chronic graft-versus-host disease (cGVHD) patients." (PMID 34631716, 2021). "To elucidate these regulatory mechanisms, we examined the role of inhibitory coreceptors on Tregs during IL-2 therapy in a murine model and in patients with chronic GVHD." (PMID 34526990, 2021). "After the assessment period, four patients developed chronic GVHD at day+31 (severe), day+72 (moderate), day+192 (mild), and day+346 (moderate) post IL-2 NK cell infusion, corresponding to days 142, 155, 267, and 446 after allo-HSCT, respectively." (PMID 34071607, 2021). "Low-dose IL-2 therapy increased circulating Tregs and improved clinical symptoms of chronic GVHD; however, the mechanisms that regulate Treg homeostasis during IL-2 therapy have not been well studied." (PMID 34526990, 2021).
chronic graft versus host disease (continued). "Low-dose IL-2 therapy also has been shown to be efficacious in the treatment of steroid-refractory chronic GVHD in phase I/II clinical trials." (PMID 34575843, 2021). "Further studies are needed to determine the optimal dosage, timing, duration, and combination of low-dose IL-2 therapy in patients with chronic GVHD." (PMID 34526990, 2021). "Administration of low-dose IL-2 can diminish inflammation and ameliorate disease in patients suffering from chronic graft-versus-host disease." (PMID 32104703, 2020). "For example, in chronic graft-versus-host disease, ld-IL-2 improved the manifestation of the disease at multiple sites in the majority of glucocorticoid-resistant patients." (PMID 29615964, 2018). "IL-2 was also shown to have beneficial effects for the treatment of chronic graft-versus-host disease (GVHD), an alloimmune inflammatory disease occurring after allogeneic haematopoietic stem cell transplantation." (PMID 29527328, 2018). "Herein, we investigated the prophylactic and therapeutic effect of two IL-2 complexes (JES6/IL-2 and S4B6/IL-2) on SLE-like symptoms resulting from chronic GvHD." (PMID 29670626, 2018). "Over the last 20 years we have progressed from discovering that IL-2 and IL-2RA are genetically associated with autoimmune diabetes and the functional state of Tregs to seeing dramatic clinical success with IL-2 in chronic GVHD." (PMID 25457307, 2015). "A phase I dose-escalation trial of IL-2 in 28 patients with chronic GVHD after stem cell transplantation demonstrated beneficial effects of low-dose IL-2 by inducing selective expansion of functional Tregs and clinical improvement." (PMID 25322151, 2014). "In a phase 1 dose-escalation trial of subcutaneous IL-2 to treat active chronic GVHD, daily low-dose IL-2 was well-tolerated and led to sustained Treg expansion with improvement in GVHD manifestations." (PMID 24575095, 2014). "Recently, a phase I escalation study of IL-2 administration to 29 patients with active steroid-refractory chronic GVHD was performed." (PMID 23737813, 2013). "By contrast, acute GVHD could be converted to a chronic GVHD phenotype with skewing of serum Ig to IL-4 dependent isotypes (IgG1, IgE) after IL-2 blockade." (PMID 38915570, 2024). "In D2→F1 chronic GVHD, D2 mice have a naturally occurring defect in initial IL-2 production that results in skewing of the initial donor CD4 T cell response away from a Th1 program, instead promoting the differentiation of T follicular helper (Tfh) cells and enhanced IgG antibody production." (PMID 38915570, 2024). "Clinical trials have shown that prophylactic low dose IL-2 administration during the early post-transplant period could effectively enhance Treg expansion and decrease the incidence of acute and chronic GVHD." (PMID 34575843, 2021). "However, IL2 has recently been shown to improve clinical outcome in chronic graft versus host disease in steroid‐refractory patients." (PMID 34152692, 2021). "The administration of low-dose IL-2 is of interest in the treatment of chronic GVHD, and has been associated with expansion of Tregs, suppression of conventional T cell proliferation, and long-term reduction of chronic GVHD symptoms." (PMID 32411139, 2020). "In addition, ld-IL-2 was also shown to improve chronic graft-versus-host disease, which is considered as an alloantigen-induced chronic inflammation, after hematopoietic stem cell transplantation." (PMID 29615964, 2018). "The effects of IL-2/mAb complexes on Tregs and migration to GCs are better understood through an experiment using chronic graft-versus-host disease (cGVHD) in which administration of IL-2/mAb complexes increased splenic Tregs and TFR while ameliorating cGVHD without increasing TFH." (PMID 28599652, 2017).
chronic graft versus host disease (continued). "On the other hand, prevalence of chronic GVHD is characterized by constitutive phosphorylation of Stat5 in conventional CD4+ T cells (Tcons) associated with elevated amounts of IL-7 and IL-15 and relative functional deficiency of IL-2." (PMID 28819653, 2017). "Although IL-2 has been used to augment immune responses to treat cancer and persistent viral infections, it also effectively suppressed immune responses in chronic graft-versus-host disease and hepatitis C virus-induced vasculitis." (PMID 25629163, 2015). "Administration of daily subcutaneous low-dose IL-2 rapidly induced preferential and sustained Treg expansion, reversed advanced fibrotic and sclerotic manifestations of chronic GVHD in a substantial proportion of patients, and permitted a substantial reduction in glucocorticoid dose." (PMID 23737813, 2013). "Previous work has shown that IL-2, IL-6, TNF-α and IFN-γ secretion is associated with acute graft-versus-host disease, whilst increased circulatory levels of IL-6 have been associated with chronic graft-versus-host disease." (PMID 20718971, 2010). "In contrast to the control group, the 5‐year incidence of chronic GVHD (cGVHD) was lower (p = 0.018), and GVHD progression‐free survival (GPFS) was better (p = 0.025) in the IL‐2 group." (PMID 41550465, 2026). "GVHD prophylaxis using calcineurin inhibitors (cyclosporin or tacrolimus) reduce the expansion of effector T cells (Teff) by blocking IL-2 and prevent acute GVHD, but fail to reduce chronic GVHD." (PMID 34489966, 2021). "Therefore, in this study, we investigated the effects of the combination of IL-2 and a calcineurin inhibitor on Tregs and disease symptoms in a murine model of SLE-like chronic GVHD (cGVHD)." (PMID 38665907, 2024). "Complementary or additive to low dose IL-2, the adoptive transfer of Tregs or the more specialized TFR cells could thus have a high potential in chronic GVHD, although more work is needed to determine how to best deploy TFR cells therapeutically." (PMID 34575843, 2021). "In this trial, a total of 29 patients were enrolled, and the maximum tolerated dose of IL-2 was 1 × 106 IU/m2; none of the patients experienced progression of chronic GVHD or relapse of hematologic cancers." (PMID 34526990, 2021). "On the other hand, recent studies have suggested that low-dose IL-2 therapy suppresses the immune system in patients with chronic graft-versus-host disease (GVHD) and hepatitis C virus (HCV) related vasculitis, and these studies have also shown that low-dose IL-2 increases the number of Treg cells." (PMID 25089268, 2014). "Shortly after the study began, they observed higher levels of pSTAT5 in Teffs than Tregs in patients with chronic GVHD without IL-2 administration compared to rapidly reversed signaling imbalance between Treg and Teff in those with low-dose IL-2 therapy." (PMID 25322151, 2014). "Although the combination of calcineurin inhibition and IL-2 might be detrimental in acute GVHD as shown by our current study, it could be still effective in chronic GVHD." (PMID 24658577, 2014). "We examined whether addition of IL-2 restores the Treg proportion even with concurrent use of a calcineurin inhibitor and if the follicular helper T cell (Tfh) proportion is reduced in an SLE-like murine chronic graft versus host disease model." (PMID 38665907, 2024).
metastatic disease (45 papers, 1998 to 2025). "In patients with metastatic disease, several options are now available (namely ipilimumab, nivolumab, pembrolizumab, cytotoxics, interleukin-2, anti-MEK, and anti-BRAF agents in BRAF mutated MM), and so long-term survivors are a realistic possibility." (PMID 27368007, 2016). "The nature of the metastatic disease, the short half-life of recombinant IL-2 and its preferential affinity for Tregs indicate that a high-dose bolus of intravenous IL-2 is needed, resulting in peripheral immune cell activation and systemic toxicity." (PMID 40410571, 2025). "Inhaled IL-2 and IL-15 have also been used to treat dogs with pulmonary metastatic disease, and a statistically insignificant increase in macrophage numbers in bronchoalveolar lavage samples was noted after IL-2 therapy." (PMID 37090720, 2023). "Although their results showed that patients with mRCC benefited from high-dose IL-2, severe complications and metastatic diseases still occurred." (PMID 35967367, 2022). "In a clinical study on TILs combined with IL-2 in CRC, patients in the ACT group received TILs extracted from metastatic tumors, as stimulated and amplified with high-dose IL-2, whereas the control group received traditional chemotherapy." (PMID 34925375, 2021). "High dose IL-2 has been approved as monotherapy for some metastatic disease, and multiple clinical trials are underway to investigate IL-2 in combination with chemotherapies or other immunotherapies." (PMID 32244756, 2020). "The mean time between diagnosis of metastatic disease and initiation of HD IL-2 was 22.4 (0.8–55.8) months for the mM patients and 31.8 (0.2–156.0) months for the mRCC patients." (PMID 30777131, 2019). "Immunization at day 7 with C57BL/6 PBMCs resulted in a decrease in Tregs to 10.0 ± 2.9% and 14 ± 3.2 in spleen and metastatic tumour, respectively and a decrease serum IL-10/IL-2 ratio." (PMID 31683642, 2019). "Thirty-nine patients were immunotherapy-naive for advanced or metastatic disease, and 11 had received prior immunotherapy (immune checkpoint inhibitor, interferon, IL-2, or other) for advanced or metastatic disease." (PMID 30894212, 2019). "In contrast, the level of IL-2 was enhanced with 37.9 pg/ml of GA in metastatic tumour-bearing C57BL/6 mice." (PMID 28775294, 2017). "Prior to the advances in therapeutics seen over the last decade, the mainstay of treatment for metastatic disease was cytokine-based treatment with high dose interleukin-2 (IL-2) and interferon-alpha (IFN-α) after their FDA approval in the 1990s." (PMID 28153029, 2017). "Response to HD IL-2 and site of metastatic disease also correlated significantly with progression-free and overall survival." (PMID 28923120, 2017). "Between 2005 and 2012, six new therapies were approved for patients with metastatic disease, in addition to the older therapies of interferon and high-dose interleukin-2 (IL-2)." (PMID 28326277, 2016). "Pazopanib and sunitinib represent the standard-of-care options we prefer for initial therapy in most patients with metastatic disease, with temsirolimus and IL-2 playing a role in limited situations." (PMID 28326277, 2016). "The mean time between diagnosis of metastatic disease and initiation of HD IL-2 was 18 months (0.2-80) in patients previously treated with ipilimumab and 7 months (0.03-98) in patients with no prior ICB." (PMID 27660706, 2016). "The group of 36 patients who received IL-2 as first-line treatment for metastatic disease had 9 patients within the clinical benefit group (25%)." (PMID 25815245, 2015). "The best response was observed in Patient 3, the patient who started HD IL-2 therapy with metastatic disease limited to the lungs only (after complete radiosurgical response of a solitary brain lesion prior to treatment)." (PMID 23762555, 2013).
metastatic disease (continued). "We have previously shown that immunotherapy using agonist CD40 antibodies combined with high doses recombinant human IL-2 results in synergistic anti-tumor responses against metastatic disease in tumor bearing mice." (PMID 23133545, 2012). "All patients had received prior therapy for metastatic disease, which included IL2 (4 patients) and/or IFN-α2b (7 patients) in all patients based on the study eligibility of requiring prior cytokine-based therapy to participate in this study." (PMID 19640287, 2009). "The median survival from the time of identification of metastatic disease is 444 days in the IL-2 arm and 381 days in the IL-2/IFN-alpha arm." (PMID 9703284, 1998). "The study included 19 evaluable metastatic renal cell cancer patients, who received s.c. low-dose IL-2 (6 MIU day(-1) for 6 days per week for 4 weeks) as a first-line immunotherapy of their metastatic disease." (PMID 9667674, 1998). "The combination of IL-2 and Mel may stabilize the disease and increase the survival of patients with metastatic tumors." (PMID 38668052, 2024). "Pre-treatment LDH values and site(s) of metastatic disease may be useful markers to select patients at greater likelihood of benefit to HD IL-2 therapy." (PMID 28923120, 2017). "For a small group of patients for whom cure is possible from metastatic disease, IL-2 is promising; however, in attempting to reduce toxicity, some regimens may negate the possibility of response." (PMID 26557408, 2015). "All patients had active metastatic disease at the time of accrual, and all had failed at least two previous treatments including Dacarbazine-containing regimens (13 patients) or ambulatory doses of IL-2 (4 patients)." (PMID 23365757, 2013). "Other treatment options in the metastatic disease setting include high-dose interleukin 2 (IL-2), which achieves durable long-term complete responses in a small proportion of patients treated but has yet to be formally compared to dacarbazine in a randomized phase III study." (PMID 22220281, 2011). "As RCC is highly resistant to chemotherapy, and its response to cytokine therapy including high-dose interleukin-2 (IL-2) and/or interferon-alfa is less than 20%, the outcome for patients with metastatic disease is dismal: The 5-year overall survival rate despite systemic treatment is less than 10%." (PMID 19622166, 2009). "Furthermore, an appreciation of RCC as an immunogenic tumor emerged from the antitumor activity of cytokines such as interleukin 2 (IL-2) and interferon alfa (IFNα), as well as the observation of spontaneous resolution of metastatic disease after removal of the primary RCC." (PMID 35128482, 2022). "In addition, this study found that pre-treatment level of lactate dehydrogenase (LDL) and sites of metastatic disease may be useful markers for patients who benefit from HD IL-2 therapy." (PMID 31998135, 2019). "We conducted a therapeutic trial with YM155 alone, IL-2 alone, and the combination of YM155 with IL-2 to determine their antitumor effects on the progression of both orthotopic and lung metastatic tumors in a luciferase-expressing RENCA mouse model of RCC." (PMID 26023798, 2015). "The only two treatment alternatives available for inoperable or metastatic disease until a few years ago were interferon alpha (IFN-α) and interleukin 2 (IL-2) therapy." (PMID 23254966, 2013). "Earlier treatment for patients with metastatic disease [including the initially diagnosed metastatic RCC (mRCC) patients] relied on several cytokines, such as interferon alfa (IFN-α) and interleukin-2 (IL-2), which aimed to activate the antitumor immune system." (PMID 36765892, 2023). "In Europe, the use of IL-2 is usually recommended only in the context of a clinical trial; however, in patients with metastatic disease who do not have access to a clinical trial program or targeted therapy, IL-2 can be prescribed." (PMID 27372293, 2016).